RHOA (ras homolog family member A)
Diseases named in the same sentence as RHOA in open-access papers (continued):
Sharing a sentence is not in itself a finding about the gene and the disease.
breast carcinoma (continued). "Nevertheless, RhoA and RhoB expression pattern has not been studied in the different subtypes of breast cancer and our study is the first to show a specific Rho expression pattern in basal-like/triple negative breast cancer." (PMID 33162807, 2020). "Moreover, EGFR has been reported to interact with AHR and GPER (G protein estrogen receptor) to stimulate breast cancer progression and EGFR can bypass RhoA to activate YAP signaling to promote hepatocellular carcinoma proliferation." (PMID 32546278, 2020). "The MetaCore pathway analysis suggested that “signal transduction: angiotensin II/angiotensin II receptor type 1 (AGTR1) signaling via Ras homolog family member A (RhoA) and c-Jun N-terminal kinase (JNK)” had a high correlation with breast cancers exhibiting PODXL2 expression." (PMID 32669966, 2020). "In this study, using the highly metastatic 4T1 orthotopic mouse model, which closely resembles the human triple negative breast cancer, we show that downregulation of RhoA expression increases breast cancer lung metastasis." (PMID 31705019, 2019). "While reduced RhoA expression significantly increased breast cancer cells invasion through Matrigel, it did not have a noticeable effect on cell proliferation as measured by two different assays." (PMID 31705019, 2019). "To test the role of RhoA and RhoC in M2a-induced breast cancer cell migration, we stimulated MDA-231 or SUM-149 wild type (WT), RhoA CRISPR-Cas9 knockout (ΔRhoA), or RhoC CRISPR-Cas9 knockout (ΔRhoC) with either base media or M2a conditioned media and monitored wound closure over 24 h." (PMID 31214501, 2019). "At present, the mechanism of how RhoA can have opposite effects on breast cancer cell invasion in vitro is not known." (PMID 31705019, 2019). "We noted that the ARHGEF1 i.p. generated from lysates of breast-cancer PDX treated with cortactin siRNA had less capacity to generate activated RhoA than the ARHGEF1 i.p. of PDX treated with control, nonspecific siRNA." (PMID 31667337, 2019). "For instance, Rhosin, which disturbs RhoA activation by binding to its W58 and impeding the docking of GEF enzymes, can inhibit breast cancer cell proliferation, migration and invasion in vitro and restrain the formation of spheroid bodies in gastric cancer cells." (PMID 30884855, 2019). "RhoA is involved in Wnt5a signaling and promotes the migration of MDA-MB-231 breast cancer cells." (PMID 28289332, 2017). "Further analysis is necessary to examine whether A77636′s action on Rac1 GTPase and/or RhoA GTPase may regulate matrix metalloproteinases such as MMP2 and MMP9 that may drive migration of breast cancer cells." (PMID 28374823, 2017). "Unlike in breast cancer, the proposed mechanism for suppression of RhoA is through MLK3 binding and sequestration of p63RhoGEF." (PMID 27213454, 2016). "RhoA- and RhoC-induced gene transcription via the actin-regulated transcriptional co-activator megakaryocytic leukemia (MKL) and serum response factor (SRF) drive metastasis in breast cancer and melanoma." (PMID 27600078, 2016). "Besides, estrogen-dependent PI3K activation has also been reported to enhance cell motility and invasion by activating the RhoA/ROCK-2 cascade and ezrin activity in breast cancer cells." (PMID 26845172, 2016). "Moreover, RHOA is necessary for CFL1 phosphorylation and cell migration induced by CD74 in breast cancer cells." (PMID 27626171, 2016). "We observed an increase of ERR1 expression at both mRNA and protein levels and a concomitant decrease of RhoA expression after knockdown of NRF2 in breast cancer cell lines, with no changes in CULLIN3 or BACURD1." (PMID 27713154, 2016). "For example, it was recently reported that siRNA directed against hCE1 (PMPMEase), but not CES2, inhibited RhoA demethylation and altered the morphology of breast cancer cells." (PMID 25228915, 2014).
breast carcinoma (continued). "Moreover they also appeared in the canonical pathway analysis of ephrin A Signaling, RhoA signaling, PEDF signaling, breast cancer regulation by stathmin 1 and signaling by Rho family GTPases of antidepressant-treated women." (PMID 25628539, 2014). "Together, these data show that RhoA-dependent pathways predominate in invasive breast cancer cells in the absence of BCAR3." (PMID 23762409, 2013). "In the present study, we provide evidence demonstrating that in the highly invasive human breast cancer MDA-MB-231 cell line, activation of the GnRHR promotes RhoA activation, actin cytoskeleton remodeling and a remarkable increase in cell adhesion to substrate." (PMID 23176180, 2012). "This RhoA-independent effect was also confirmed by the absence of the effect of C3 exoenzyme on Cox-2 at transcript and protein levels on these breast cancer cells." (PMID 12771933, 2003). "Moreover, the expression of the miR-31 target genes SATB2 and RHOA was significantly reduced in SUM-159 cells after combination treatment with GBK and DDP, indicating that GBK could impair breast cancer cell migration and invasion." (PMID 36313626, 2022). "Moreover, increasing substrate stiffness may stimulate an integrin β1-activated FAK signaling, which in turn promotes the activation of RhoA/ROCK1/p-MLC and RhoA/ROCK2/p-cofilin signaling cascades toward the motility and migration of breast cancer cells." (PMID 33562737, 2021). "Therefore, to confirm the roles of these genes on the vital regulatory mechanisms in breast cancer, we compared the potential role of novel RGs (SF1, TRA2B, THRAP3, RHOA, and QRICH1) vs. traditional RGs (ACTB, and GAPDH) in the normalization of target gene expression." (PMID 34895237, 2021). "Hence, we examined whether BNIP-2 could promote or suppress RhoA activity in MDA-MB-231 cell, a highly migratory breast cancer cell line." (PMID 32789168, 2020). "It has been reported that dasatinib inhibits the migration and metastasis of canine mammary cancer cells with enhanced Wnt and HER signaling via downregulation of cSRC, and inhibits actin fiber reorganization and promotes endothelial cell permeability through RhoA-ROCK Pathway." (PMID 33344441, 2020). "Here, we also demonstrated that RhoA/ROCK1 signaling may play an important role in activation of FAK/Src/paxillin signaling, which was similar to the molecular mechanism of the hypoxia-induced breast cancer cell migration." (PMID 31558699, 2019). "Injection of RhoA or Cdc42 prevents breast cancer cells from mAb200 (Ras-GAP inhibitor)-induced apoptosis but no additional effects are seen upon Cdc42/RhoA co-injection, which demonstrates that the protective function of Cdc42 in breast cancer results from RhoA activation." (PMID 30754684, 2019). "Therefore, we aimed to study the association between dietary intake of protein and tumoral expression levels of Ras homologous gene family member A (RhoA), vascular endothelial growth factor-A (VEGF-A), and VEGF receptor-2 (VEGFR2) in primary breast cancer (BC) patients." (PMID 31333806, 2019). "Compound 1 also could not promote breast cancer cell migration in RhoA silenced cells compared with cells transfected with siCtrl alone." (PMID 27713154, 2016). "Using primary breast cancer tissues and epithelial cells, Kong and colleagues observed that miR155 can play an important role in the transforming growth factor-β induced epithelial to mesenchymal transition (TGF-β-induced EMT), cell migration and cell invasion by targeting the small G-protein RhoA." (PMID 26124926, 2015). "However, in our system miR-31 neither targeted the RhoA-3′-UTR, nor did RhoA protein expression correlate to miR-31 expression in these breast cancer cells." (PMID 25889182, 2015). "RhoA is one of such genes, which may enhance EMT in human breast cancer." (PMID 22200848, 2012).
breast carcinoma (continued). "Constitutively active ΔDAD-Daam1 induced RhoA activation, the formation of stress fibers, and migration of MCF-7 cells, indicating that Daam1 may be specifically required for the activation of Dvl2 after Wnt5a treatment in breast cancer cells." (PMID 22655072, 2012). "Notably, we previously showed that NGF may enhance RhoA activity in breast cancer cells to promote migration/invasion independent of TrkA phosphorylation." (PMID 35346305, 2022). "However, despite the described opposite effects of RhoA on in vitro breast cancer cells invasion, the effects of specific RhoA shRNA knockdown on breast cancer metastasis has never been formally addressed with an orthotopic transplantation immune-competent mouse model until now." (PMID 31705019, 2019). "Interestingly, several miRNAs could also downregulate RhoA; for example, miR-154-3p and miR-487-3p specifically repressed RhoA expression and blocked thyroid cancer cell growth; miR-101 downregulated the EMT process and breast cancer cell migration by reducing the RhoA level." (PMID 35256884, 2022). "Indeed, the migration-promoting effects and the enhanced RhoA/LIMK/Cofilin pathway induced by FMNL2 silencing could be abrogated by ZOL or BMS3, highlighting the involvement of RhoA/LIMK/Cofilin pathway in FMNL2-mediated inhibition of breast cancer cell migration and invasion." (PMID 35379791, 2022). "To eliminate possible off-target effect of shRNA and validate RKIP’s effect on RhoA activation is not species and cell lines specific, we generated additional RKIP knockdown human breast cancer cells with a different RKIP specific shRNA." (PMID 34465801, 2021). "More recently, hypoxia-inducible factor (HIF) has been shown to transcriptionally up-regulate RhoA and ROCK1, not but ROCK2, in breast cancer cell lines in response to hypoxia in 2D culture." (PMID 27203208, 2016). "Our aim in this study was to examine the effects of Rac3 in breast cancer cell aggressivity in both the invasive MDA-MB-231, which have a spontaneous activation of RhoA, and in the non-invasive MCF-7, which do not." (PMID 23388133, 2013). "In addition, Rho GTPases regulate many pathways important in the malignant phenotype, and CDC42 activity (but not RhoA or Rac1) is required for TEM and metastatic progression in prostate and breast cancer models." (PMID 34374417, 2021). "To answer these questions, we examined the consequences of Rac3 inhibition by siRNA in two breast cancer cell lines: MDA-MB-231 (Estrogen Receptor (ER) negative), an aggressive line that overexpresses constitutively activated RhoA; and MCF-7 (ER positive), which is not invasive." (PMID 23388133, 2013). "For example, although podoplanin can induce RhoA activation and an epithelial-mesenchymal transition (EMT) in MDCK cells, it attenuated RhoA activity and could not induce EMT in a breast carcinoma cell line, suggesting that podoplanin exerts cell type-specific functions." (PMID 21034514, 2010).
gastric cancer (130 papers, 2006 to 2025). A primary or metastatic malignant neoplasm involving the stomach. "Further complicating the metabolic dynamics within the TME is the occurrence of mutations in ras homolog family member A (RHOA) in certain gastric cancer cells." (PMID 40028336, 2025). "In gastric cancer, the Y42 mutation of tumor RHOA was observed, which increased the production of free fatty acids in GC cells by activating the PI3K-AkT-mTOR signalling pathway." (PMID 36387147, 2022). "A recent study has shown raised production of FFAs by RHOA Y42-mutated gastric cancer, modulated via the PI3K pathway, which favors the accumulation of Tregs in a low-glucose TME." (PMID 36203151, 2022). "Previous studies in gastric cancer found that RHOA Y42 mutation in cancer cells produced excessive fatty acids by upregulating fatty acid synthase (FASN)." (PMID 35983074, 2022). "Combined use of PI3K inhibitors and PD-1 inhibitors was found to significantly reduce resistance to PD-1 in RHOA Y42 mutated gastric cancer." (PMID 36387147, 2022). "Y42C mutation of RhoA has a higher protein level, which can promote the proliferation and movement of gastric cancer cells.As for EGFR, its activation is associated with the E-cadherin expression." (PMID 34422902, 2021). "In 8% of gastric cancer patients, the oncogenic driver mutation in RHOA (Y42) in tumor cells leads to the activation of the PI3K/AKT/mTOR pathway and increases the production of FFA that favors Treg survival." (PMID 33924428, 2021). "Among the various genomic alternations that occur in gastric cancer, RHOA mutation plays a critical role in the development and progression of cancer by regulating actin organization, cell migration, cytokinesis and the cell cycle." (PMID 33288739, 2020). "Our findings are supported by previous results, not only regarding the role of RhoA in tumor cell invasion and metastasis but also regarding the association of RhoA activity with gastric cancer prognosis." (PMID 33288739, 2020). "Here, we reviewed literature of how RHOA’s roles, in gastric cancer (GC), associate with the second-generation cancer hallmark term, “activation of invasion and metastasis”." (PMID 31156701, 2019). "We inspected RHOA mutations, copy number variations, and gene expression the TCGA stomach cancer dataset (258 patients) by using cBio Portal." (PMID 31156701, 2019). "In the present study, the contribution of RHOA mutations to tumor morphology was investigated using an orthotopic xenograft model using the gastric cancer cell line MKN74, in which wild-type (WT) or mutated (Y42C and Y42S) RHOA had been introduced." (PMID 31485674, 2019). "Diffuse-type gastric carcinomas reportedly possess mutations at Arg5, Gly17, and Tyr42 of RhoA, which cause RhoA gain-of-function and a poor prognosis." (PMID 29659486, 2018). "Several recent studies involving the use of whole-exome or whole-genome sequencing have reported recurrent nonsynonymous mutations of RHOA in a subset of gastric cancers." (PMID 25823974, 2016). "We performed a thorough review of 87 diffuse-type gastric cancers, including 22 RHOA-mutated and 65 RHOA wild-type gastric cancers." (PMID 25823974, 2016). "This study was the first to perform a thorough clinicopathology review of RHOA-mutated gastric cancers." (PMID 25823974, 2016). "RHOA mutated gastric cancer cells reduced the secretion of CXCL10 and CXCL11, and stimulated the synthesis of fatty acids through the PI3K-AKT-mTOR pathway, which in turn enhances the inhibition of regulatory T cells (Tregs) within the TIME, thereby inducing immunosuppression." (PMID 40149008, 2025). "Besides, IL-6 was found to activate Ras homolog family member A/Rho-associated protein kinase (RhoA/ROCK) signaling pathway in human gastric cancer cells." (PMID 40682111, 2025).
gastric cancer (continued). "First, RhoAG17V mutations of gastric carcinomas may confer structural resistance to canonical inhibitors like SC by stabilizing GTP-bound RhoA, necessitating mutant-allele-specific therapeutic development." (PMID 40746849, 2025). "However, whole‐genome sequencing analysis in gastric cancer proved that RHOA mutation in diffuse‐type tumors promoted anoikis escape, and the most disturbed pathway in gastric cancer happens to be adherens junction and focal adhesion." (PMID 39286778, 2024). "Another study showed that the RHOA Y42 mutation induced abundant free fatty acid (including omega-3 PUFAs) production in cell line culture, which contributed to the immunosuppressive function of Treg cells that promoted progression of gastric cancer." (PMID 38136676, 2023). "SB-PCCs may harbor RHOA mutations, which are reminiscent of the diffuse subtype of gastric cancers or appendiceal GCAs, while KRAS and PIK3CA mutations, commonly involved in colorectal and small bowel adenocarcinomas, are not typical of such cancers." (PMID 36812376, 2023). "Similarly, the expression levels of FAS, CPT-1, PPARα, and PPARɣ were also higher in gastric cancer with RHOA Y42 mutation." (PMID 36203151, 2022). "Human gastric cancer cells bearing RHOA gene mutations exhibited increased FAS via the stimulation of the PI3K-AKT-mTOR axis, and the enhanced free fatty acid (FFA) availability in the TME was competitively consumed by Tregs to fuel FAO for recruitment and function." (PMID 35948909, 2022). "In patients with lymphoma, RHOA mutations were assessed as a potential biomarker for poor prognosis, and gain-of-function mutations were studied as a possible therapeutic target for gastric cancer." (PMID 36232418, 2022). "A recent study found that RhoA Y42 mutation is associated with poor prognosis of gastric cancer." (PMID 34422902, 2021). "Apart from the PI3K/AKT pathway, CNTN1 is also associated with the RhoA pathway in gastric cancer; VEGF-C/VEGFR-3 pathway in lung, gastric, and esophageal cancers, and OSCC; α7 nAChR/ERK and Src-p38 MAPK-C/EBPα pathways in lung cancer; and Notch1 and RET/PTC3 pathways in thyroid cancer." (PMID 33194679, 2020). "Noticeably, a single patient with RHOA-mutated early cancer (pT1b) developed pulmonary hypertension due to pulmonary tumor thrombotic microangiopathy that was caused by gastric cancer, which was revealed by video-assisted thoracic surgery and subsequent autopsy." (PMID 25823974, 2016). "Notably, RHOA mutation has been detected almost exclusively in diffuse-type gastric cancers, accounting for 14–25 % of the cases of this type, whereas it is absent in intestinal-type cancers." (PMID 25823974, 2016). "Moreover, the increased expression of RhoA and Rac1 among the Rho-GTPase family proteins is associated with gastric cancer progression." (PMID 27333045, 2016). "It was also discovered that the RhoA/ROCK signaling pathwayparticipates in the mechanism of hypertension resulting from apatinib treatmentin mice in a gastric cancer model." (PMID 40160560, 2025). "For example, in gastric cancer, FBXW7 causes apoptosis, arrests growth, and inhibits epithelial-mesenchymal transition by enhancing RhoA ubiquitination and proteasome degradation." (PMID 39823500, 2025). "RhoA drives the malignant progression of gastric cancer through cytoskeletal remodeling and the regulation of epithelial-mesenchymal transition (EMT)." (PMID 40746849, 2025). "USP11 enhances the effectiveness of chemotherapy in gastric cancer by RhoA and Ras signaling pathways." (PMID 39605891, 2024). "And in Takayoshi Kaida study, C5a receptor (CD88) promoted motility and invasiveness of gastric cancer by activating RhoA." (PMID 39850877, 2024).